ARHGAP35 (Rho GTPase activating protein 35)
Description:
Rho GTPase-activating protein (GAP). Binds several acidic phospholipids which inhibits the Rho GAP activity to promote the Rac GAP activity. This binding is inhibited by phosphorylation by PRKCA. Involved in cell differentiation as well as cell adhesion and migration, plays an important role in retinal tissue morphogenesis, neural tube fusion, midline fusion of the cerebral hemispheres and mammary gland branching morphogenesis (By similarity). Transduces signals from p21-ras to the nucleus, acting via the ras GTPase-activating protein (GAP) (By similarity). Transduces SRC-dependent signals from cell-surface adhesion molecules, such as laminin, to promote neurite outgrowth. Regulates axon outgrowth, guidance and fasciculation (By similarity). Modulates Rho GTPase-dependent F-actin polymerization, organization and assembly, is involved in polarized cell migration and in the positive regulation of ciliogenesis and cilia elongation (By similarity). During mammary gland development, is required in both the epithelial and stromal compartments for ductal outgrowth (By similarity). Represses transcription of the glucocorticoid receptor by binding to the cis-acting regulatory sequence 5'-GAGAAAAGAAACTGGAGAAACTC-3'; this function is however unclear and would need additional experimental evidences.
Synonyms: GRF-1; p190-A; GRLF1; KIAA1722; P190A; p190ARHOGAP; p190RhoGAP
Tractability: Small molecule: a structure with a bound ligand is known; it has a binding pocket of medium quality. Antibody: UniProt places it where antibodies can reach, with medium confidence; its Gene Ontology location is reachable by antibodies, with medium confidence. PROTAC: ubiquitination databases record sites on it; its protein half-life has been measured.
Gene: Protein-coding gene on chromosome 19 (46,860,997 to 47,005,077, forward strand). Ensembl gene ENSG00000160007.
Subcellular location: Cytoplasm, cytoskeleton, cilium basal body; Cytoplasm; Nucleus; Cell membrane
Subcellular location (Human Protein Atlas): Nuclear bodies; Aggresome; Microtubules
Pathways (Reactome):
Signal Transduction: CDC42 GTPase cycle; PTK6 Regulates RHO GTPases, RAS GTPase and MAP kinases; RAC1 GTPase cycle; RAC2 GTPase cycle; RAC3 GTPase cycle; RHOA GTPase cycle; RHOB GTPase cycle; RHOC GTPase cycle; RHOD GTPase cycle; RHOG GTPase cycle; RHOJ GTPase cycle; RHOQ GTPase cycle; RND1 GTPase cycle; RND2 GTPase cycle; RND3 GTPase cycle
Developmental Biology: Sema4D mediated inhibition of cell attachment and migration
Gene Ontology:
Molecular function: GTPase activator activity; phospholipid binding; GTP binding; GTPase activating protein binding; GTPase activity; protein-containing complex binding
Biological process: axon guidance; axonal fasciculation; cell migration; central nervous system neuron axonogenesis; establishment or maintenance of actin cytoskeleton polarity; mammary gland development; negative regulation of Rho protein signal transduction; neuron projection guidance; positive regulation of cilium assembly; positive regulation of neuron projection development; regulation of actin cytoskeleton organization; regulation of actin polymerization or depolymerization; regulation of axonogenesis; regulation of cell size; regulation of small GTPase mediated signal transduction; Rho protein signal transduction; wound healing, spreading of cells; signal transduction
Cellular component: ciliary basal body; cytosol; actin cytoskeleton; cytoplasm; nucleus; plasma membrane
Genetic constraint (gnomAD): Loss-of-function variants: 15 observed, 113.25 expected, observed/expected ratio (o/e) 0.13, 90% interval 0.088 to 0.2. The upper end of that interval is the gene's LOEUF score, 0.2, which puts it in group 1 of 6, group 1 being the genes least tolerant of losing a copy. Missense variants: 1,257 observed, 1,956.3 expected, observed/expected ratio (o/e) 0.64, 90% interval 0.61 to 0.67. Synonymous variants: 642 observed, 744.48 expected, observed/expected ratio (o/e) 0.86, 90% interval 0.81 to 0.92.
Cancer hallmarks: invasion and metastasis (suppresses); proliferative signalling (promotes); suppression of growth (promotes); escaping programmed cell death (promotes); angiogenesis (suppresses); invasion and metastasis (promotes); escaping programmed cell death (suppresses)
Homologues: Orthologues: macaque ARHGAP35 (99% identical), dog ARHGAP35 (99% identical), pig ARHGAP35 (99% identical), chimpanzee ARHGAP35 (98% identical), guinea pig ARHGAP35 (98% identical), mouse Arhgap35 (98% identical), rat Arhgap35 (98% identical), rabbit ARHGAP35 (89% identical), tropical clawed frog arhgap35 (77% identical), zebrafish arhgap35a (70% identical). Paralogues in human: SYDE2 (14% identical), SYDE1 (9% identical), CHN2 (7% identical), CHN1 (7% identical).
Diseases named in the same sentence as ARHGAP35 in open-access papers:
ARHGAP35 is named in the same sentence as 59 diseases in open-access papers, as found by Europe PMC text mining. Sharing a sentence is not in itself a finding about the gene and the disease. The quoted sentences say what the papers report.
breast carcinoma (11 papers, 2013 to 2023). "A previous study demonstrated that cadherin-induced entosis was associated with ARHGAP35 activity-dependent polarized distribution in human breast cancer cells." (PMID 35758029, 2022). "Recent data have shown that this protein can regulate cell proliferation and the dysregulation of ARHGAP35 may be associated with gliomas and breast cancer." (PMID 25136583, 2014). "Their results show ARHGAP35 activation promotes breast cancer growth, migration, and invasion, and provide important evidence for the crucial roles of this Brk-ARHGAP35 signaling pathway in promoting breast malignancy." (PMID 25136583, 2014). "In breast cancer, a breast cancer kinase could phosphorylate ARHGAP35, which in turn could regulate Rho and Ras and promote cancer cell growth, migration and invasion." (PMID 35758029, 2022).
colorectal cancer (5 papers, 2019 to 2022). A primary or metastatic malignant neoplasm that affects the colon or rectum. "Abnormal expression of ARHGAP35 in colorectal cancer patients was associated with poor survival." (PMID 30886832, 2019). "TRIM65 accelerates colorectal cancer metastasis by targeted degradation of ARHGAP35 protein, promotes the invasion of endometrial stromal cells through DUSP6 ubiquitination, activates ERK1/2/C-myc signals, and promotes bladder cancer cells through ubiquitination and degradation of ANXA2 invasion." (PMID 36035221, 2022). "TRIM65 has also been shown to promote colorectal cancer metastasis through targeted ubiquitination and degradation of ARHGAP35 protein and activates ERK1/2/C-myc signaling by targeting ubiquitination to degrade DUSP6 protein, thereby promoting the invasion of endometrial stromal cells." (PMID 36035221, 2022). "Similarly, we also found that circARHGAP35 was upregulated and linear ARHGAP35 was downregulated in a 62 paired colorectal cancer (CRC) patients' cohort." (PMID 34258149, 2021). "We show that circARHGAP35 and linear ARHGAP35 mRNA have antithetical expression and functions in hepatocellular carcinoma (HCC) and colorectal cancer (CRC)." (PMID 34258149, 2021).
endometrial cancer (4 papers, 2019 to 2023). Primary or metastatic malignant neoplasm involving the endometrium (mucous membrane that lines the endometrial cavity). "ARHGAP35, the gene encoding P190A, is mutated in approximately 15% of endometrial cancers." (PMID 35409214, 2022). "It should be noted that inactivation of ARHGAP35 leads to abnormal activation of RhoA in endometrial cancer and promotes the malignant transformation of tumor cells through the Hippo-Yap pathway, consistent with the conclusions reported in this study." (PMID 36691027, 2023). "However, inactivating mutation status of ARHGAP35 remains unknown in endometrial carcinoma." (PMID 30886832, 2019). "According to our MutSigCV result, ARHGAP35 is not predicted to be a true cancer driver gene, but a pan-cancer study suggested it may contribute to oncogenesis of endometrial cancer." (PMID 30886832, 2019).
osteosarcoma (4 papers, 2014 to 2021). A usually aggressive malignant bone-forming mesenchymal neoplasm, predominantly affecting adolescents and young adults. "Like tumor grade, ARHGAP35 rs1052667 polymorphism was an independent prognostic factor influencing the survival of osteosarcoma." (PMID 25136583, 2014). "We found that osteosarcoma patients having genotypes with ARHGAP35 rs1052667 T alleles had a significant poor RFS and OS compared to those without T alleles." (PMID 25136583, 2014). "In summary, to the best of our knowledge, this is the first report investigating an association between ARHGAP35 rs1052667 polymorphism and osteosarcoma risk and prognosis in Guangxi patients." (PMID 25136583, 2014). "To evaluate possible interactive effects of matching factors (including gender, age, and race) and ARHGAP35 rs1052667 polymorphism on osteosarcoma risk, we performed a series of bivariate stratified analyses by matching factors." (PMID 25136583, 2014). "We have found evidence that the genotypes of ARHGAP35 rs1052667 T alleles may be correlated with increased risk and poor prognosis for osteosarcoma and that this polymorphism may be involved in the tumorigenesis of this type of tumor." (PMID 25136583, 2014). "Additionally, we also investigated the association between ARHGAP35 rs1052667 polymorphism and osteosarcoma prognosis." (PMID 25136583, 2014). "Multivariate cox regression analysis (with stepwise forward selection based on likelihood ratio test) was next performed to determine whether ARHGAP35 rs1052667 polymorphism was an independent predictor of osteosarcoma cases." (PMID 25136583, 2014). "Considering the difference of the treatment and to explore whether this difference affected the modifying role of ARHGAP35 rs1052667 polymorphism, we stratified the analysis of the effects of ARHGAP35 genotypes on osteosarcoma outcome by the treatment status." (PMID 25136583, 2014). "Therefore, we specifically conducted a hospital-based case-control study to examine whether ARHGAP35 rs1052667 polymorphism modifies osteosarcoma risk and prognosis." (PMID 25136583, 2014). "Thus, ARHGAP35 polymorphism might play an important role in the tumorigenesis of osteosarcoma, and this provided a new genetic insight into osteosarcoma tumorigenesis." (PMID 25136583, 2014). "Moreover, as a polymorphism in the 3′-UTR of ARHGAP35 gene is associated with tumor size, tumor grade, tumor metastasis, and survival (overall and recurrence-free) of patients, p190A was proposed as an independent prognostic factor influencing survival of patients with osteosarcoma." (PMID 31013840, 2019). "In accordance with these reports, our present study exhibited that ARHGAP35 might be involved in osteosarcoma tumorigenesis." (PMID 25136583, 2014). "Likelihood ratio tests for interaction of the stratified variables and ARHGAP35 genotypes showed that these matching factors did not modulate the effects of this polymorphism on osteosarcoma risk (Pinteraction > 0.05)." (PMID 25136583, 2014). "In the stratified analysis, no interactive effects were found, suggesting that these factors do not modify the correlation between ARHGAP35 rs1052667 polymorphism and osteosarcoma risk." (PMID 25136583, 2014). "Results showed that these osteosarcoma cases with risk genotypes of ARHGAP35, compared to those without risk genotypes, faced larger tumor size (OR is 4.85), lower tumor differentiation (OR is 4.07), and higher metastasis risk (OR is 2.78)." (PMID 25136583, 2014). "Despite the analysis of ARHGAP35 rs1052667 polymorphism, we did not analyze other polymorphisms of this gene possibly able to modify the risk of osteosarcoma." (PMID 25136583, 2014).
glioma (3 papers, 2010 to 2019). A benign or malignant brain and spinal cord tumor that arises from glial cells (astrocytes, oligodendrocytes, ependymal cells). "Consistent with a tumor-suppressor function, ARHGAP35 gene maps to the chromosomal region 19q13.3, which is also frequently deleted in gliomas, in pancreatic, ovarian, and thyroid tumors." (PMID 31013840, 2019).
lung adenocarcinoma (3 papers, 2016 to 2020). A carcinoma that arises from the lung and is characterized by the presence of malignant glandular epithelial cells. "Another intriguing discovery from cancer genome analyses is that in lung adenocarcinoma, ARHGAP35 alterations are found in tumor samples that lack mutations in genes encoding receptor tyrosine kinases (RTKs) or constituents of the RAS–ERK pathway." (PMID 32641858, 2020). "In this study, 2% of whole samples exhibit a mutation on ARHGAP35 gene and this mutational status appears significant for five tumor types: Endometrial tumors (14%), lung squamous cell carcinoma (5%), lung adenocarcinoma (3%), head and neck cancer (3%), and kidney clear cell carcinoma (1%)." (PMID 31013840, 2019). "To this end, we were aided by a recent study from others demonstrating that ARHGAP35 mutations are found in a subset of lung adenocarcinomas lacking oncogenic driver mutations in the RTK–RAS–ERK pathway." (PMID 32641858, 2020). "Indeed, ARHGAP35 was highlighted as a new gene significantly altered in lung adenocarcinoma-lacking receptor tyrosine kinase–Ras–Raf pathway or other oncogene alterations." (PMID 31013840, 2019).
lung cancer (3 papers, 2014 to 2019). A malignant neoplasm involving the lung. "In lung cancer, co-repression of STAT3 and ARHGAP35 signaling is conducive for cancer treatment." (PMID 31130822, 2019).
autosomal dominant polycystic kidney disease (2 papers, 2020 to 2023). Autosomal dominant form of polycystic kidney disease. "Polycystin-1, the major protein mutated in autosomal dominant polycystic kidney disease, activates centrosomal RhoA activity via interaction with the Rho-GAP protein ARHGAP35, resulting in shorter cilia." (PMID 32663194, 2020).
microphthalmia (2 papers, 2023 to 2024). Congenital or developmental anomaly in which the eyeballs are abnormally small. "Interestingly, mice with a full knockout of the ArhGAP35 gene display variably penetrant microphthalmia, and ARHGAP35 variants have recently been identified in humans with eye defects." (PMID 38546045, 2024). "We identified damaging variants in ARHGAP35 in five individuals from four families affected with anophthalmia, microphthalmia, coloboma and/or anterior segment dysgenesis disorders, together with variable non-ocular phenotypes in some families including renal, neurological, or cardiac anomalies." (PMID 36450800, 2023).
adenomyosis (1 paper, 2025). The growth of endometrial tissue inside the muscular wall of the uterine corpus. "Although mutations in FBXW7, ARHGAP35, PIK3R1, and PPP2R1A were also detected in adenomyosis, their frequencies were not higher than those in the normal endometrium." (PMID 40679511, 2025). "The mutation frequencies per subject, regardless of sampling depths, were as follows: in adenomyosis, KRAS: 33.3%, PIK3CA: 14.3%, and ARID1A: 14.3%, and in uterine endometrium, KRAS: 66.7%, PIK3CA: 57.1%, ARHGAP35: 52.4%, PPP2R1A: 33.3%, PIK3R1: 28.6%, and FGFR2: 19.0%." (PMID 40679511, 2025).
carcinosarcoma (1 paper, 2022). A malignant tumor composed of a mixture of carcinomatous and sarcomatous elements.
cyst (1 paper, 2020). A sac-like closed membranous structure that may be empty or contain fluid or amorphous material. "Our findings confirm these results but extend them by providing the evidence of a mechanistic link between ARHGAP35 and PC1 in cyst formation." (PMID 32663194, 2020).
frontotemporal dementia (1 paper, 2018). Frontotemporal dementia (FTD) comprises a group of neurodegenerative disorders, characterized by progressive changes in behavior, executive dysfunction and language impairment, as a result of degeneration of the medial prefrontal and frontoinsular cortices. "This is particularly meaningful because of the established RhoGAPp190 involvement in processes that are crucial for proper synaptic contacts and nerve signalling and the recent association of the human ortholog ARHGAP35 with progressive non-fluent aphasia, a subtype of frontotemporal dementia." (PMID 29652933, 2018).
gastric cancer (1 paper, 2022). A primary or metastatic malignant neoplasm involving the stomach. "However, the particular function of ARHGAP35 in gastric cancer (GC) remains unknown." (PMID 35758029, 2022).
Hyperglycemia (1 paper, 2020). An increased concentration of glucose in the blood. "Taken together, these data suggest that SELL, ITGA4, ARHGAP35, CLDN15 may be closely associated with β-cell autoimmunity in patients with LADA, and the increase of other genes in LADA may only reflect the hyperglycemia status." (PMID 33391182, 2020).
lymphoma (1 paper, 2023). A malignant (clonal) proliferation of B- lymphocytes or T- lymphocytes which involves the lymph nodes, bone marrow and/or extranodal sites. "With regards to the history of cancer in Individual 1B, while a tumor suppressor role has been identified for ARHGAP35, particularly in carcinomas, an association with lymphoma has not been reported to date so it is unclear whether this phenotype is coincidental or related to the genetic variant." (PMID 36450800, 2023).
pterygium (1 paper, 2021). A wedge-shaped fibrovascular lesion arising from the bulbar conjunctiva and extending to the cornea. "Using GEO databases, we also identified five hub genes (DSP, MXRA5, ARHGAP35, TMEM43, and OLFML2A) that were most correlated with the development of pterygium." (PMID 34249924, 2021). "After analyzing the differentially methylated m6A peaks and synchronously differentially expressed genes, we searched the Gene Expression Omnibus database and identified five genes related to the development of pterygium (DSP, MXRA5, ARHGAP35, TMEM43, and OLFML2A)." (PMID 34249924, 2021).
renal hypoplasia (1 paper, 2024). Renal hypoplasia is a developmental anomaly in which one or both kidneys (unilateral or bilateral renal hypoplasia, respectively) have a deficit in the number of nephrons and may be small. "Thus, moderately severe renal hypoplasia in Fuzzy−/− homozygotes was worsened in Fuzzy−/− embryos lacking one ArhGAP35 allele (loss of three of the four alleles)." (PMID 38546045, 2024).